BCL2 (BCL2 apoptosis regulator)
Diseases named in the same sentence as BCL2 in open-access papers (continued):
Sharing a sentence is not in itself a finding about the gene and the disease.
glioma (continued). "The selective BCL2 inhibitor ABT199 (Venetoclax) which spares the platelets, displays variable results on senescent glioma cells, in vitro." (PMID 36707509, 2023). "Anti-apoptotic BCL2 family members such as BCL2, MCL1 and BCLXL play major roles in supporting the survival and treatment resistance of gliomas and other cancers." (PMID 36831248, 2023). "Another study reports that silencing FOXD1 represses MEK-2, ERK-1, Bcl-2, DAF, and PCNA expression levels and increases Bax expression, thus repressing glioma cells’ proliferation and metastasis." (PMID 34937497, 2022). "In the brain of orthotopic glioma mice, the expression of downstream targets of PI3K/AKT signaling that regulate GBC proliferation and apoptosis resistance, e.g., Cyclin D1 and Bcl-2, was significantly increased compared with that in tumor-free brains." (PMID 36147923, 2022). "It has been found in glioma that increased Ras protein activity activates the downstream Raf/MEK/ERK signaling pathway, leading to upregulation of oncogene Bcl-2 expression and ultimately immortalizing tumor cells." (PMID 35571569, 2022). "TTFields down-regulates BCL2, up-regulates cleaved PARP and BAX, and induces apoptosis in breast cancer, ovarian cancer, and glioma cells through a caspase-dependent pathway (Ab)." (PMID 36220835, 2022). "Shikonin, a natural naphthoquinone, induces necroptosis in various cancer cell lines such as glioma, osteosarcoma, and hematopoietic cells by enhancing RIP1 and RIP3 and mROS, and also effectively overcomes P-gp, Bcl-2, Bcl-xl, MRP1, and BCRP1 drug resistance." (PMID 36500466, 2022). "In glioma, TUG1 functions as a tumor suppressor by promoting cell apoptosis via activating caspase-3 and caspase-9 mediated intrinsic pathways and inhibiting Bcl-2 mediated anti-apoptotic pathways." (PMID 35601497, 2022). "Decreased expression of Bcl-2 and DNA repair enzymes such as MGMT, ERCC-1, DNA-PK, Ku70 and Ku80 results in resistance of glioma cells to chemotherapy and radiotherapy, but these cells remain sensitive to the action of curcumin." (PMID 36268515, 2022). "We thus studied the interaction between Bcl2 and TOM20 in glioma cells upon induction of apoptosis, in control and STS-treated U251 cells, by in situ proximity ligation assay (PLA)." (PMID 33589622, 2021). "Identified miR-181 targets include Bcl-2 and MEK1, both of which are known oncogenes that facilitate glioma progression." (PMID 34440090, 2021). "For example, in vivo and in vitro experiments have shown that c-myc, CCND1, Bcl-2, BCL-XL, Survivin, etc., are the direct target genes of STAT3 in the regulation of glioma cell proliferation." (PMID 34425834, 2021). "What’s more, in vitro experiments showed that the tumor volume and mass of glioma cells injected with LINC01087 reduced markedly, and the miR-384 level increased and the Bcl-2 level decreased." (PMID 34459789, 2021). "This lncRNA negatively regulates miR-136-5p by binding as a ceRNA, thereby inhibiting Bcl-2 and Wnt2, which act downstream of the PI3K/Akt/mTOR signaling pathway, thus enhancing the glioma malignancy." (PMID 33980320, 2021). "Western blot analysis and IHC showed that cyclin D1, cyclin D2, CDK4, CDK6, Ki-67, Bcl-2 and Bax were involved in the NRXN3-induced inhibitory effect on glioma growth." (PMID 34035217, 2021). "The founding member protein Bcl-2 and Bcl-xL are anti-apoptotic proteins in the Bcl-2 family, and NH125 down-regulates the expression of Bcl-xL in glioma cells." (PMID 33673713, 2021). "The mechanisms involved in the suppression of glioma cell growth were blockage of the cell cycle in S phase by inhibition of CDK2/cyclin E1 and promotion of apoptosis through the Bcl-2/Bax pathway." (PMID 33116114, 2020). "Altogether, our study has revealed a mechanism by which CFTR promotes glioma progression via up‐regulation of Akt/Bcl2‐mediated anti‐apoptotic pathway, which warrants future studies into the potential of using CFTR as a therapeutic target for glioma treatment." (PMID 32463592, 2020).
glioma (continued). "The ratio of Bcl2/BAX and expression of MMP2 were increased in glioma cell with the KLHDC8A plasmid." (PMID 32851798, 2020). "This drug has been known to induce down-regulation of anti-apoptotic proteins Bcl-2 and XIAP and up-regulates the expression of pro-apoptotic protein Bax and caspase-3 in glioma cells." (PMID 33396819, 2020). "Then, using two glioma cell lines, SK-N-AS and U118, we further confirmed that ALO significantly promotes apoptosis by reducing Bcl2 mRNA and protein expression levels." (PMID 31534865, 2019). "Using a concentration gradient, expression of Bcl2 consistently declined in response to treatment with 0.5 and one mM ALO or 50 and 250 μM ABT199 in glioma cells." (PMID 31534865, 2019). "Both apoptotic and autophagic processes were involved in the cytotoxic effect of PP7, as PP7 activated the Bcl2/Bax pathway and the inhibition of autophagy partly rescued the toxicity of PP7 in glioma cells." (PMID 31814867, 2019). "The expression levels of global SUMOylation, SAE1, AKT, p-Akt, Cyclin D1, CDK2, p21, Bcl-2 and active Caspase-3 were increased in the SAE1-overexpressing glioma tissues." (PMID 31345225, 2019). "PIWIL1 also regulates apoptosis and cell cycle progression through P21, Cyclin D1, BCL-2 and BAX, and migration through expression of MMP-2 and MMP-9 in glioma cells." (PMID 31443431, 2019). "The high expression of p27, Bax, and Cyt-c, along with the low expression of SKP2, Bcl-2, caspase 3, PARP, and Cox-2, enhances apoptosis in glioma U87MG cells via activation of the mitochondrial-induced pathway." (PMID 30643005, 2019). "A similar result was observed in mice that contained preestablished, patient-derived glioma cells, where the decrease in tumor flux in NSC-treated mice was more substantial when NSCs were modified to overexpress Bcl-2." (PMID 30026762, 2018). "It has been shown that miR-384 targets PIWIL4 3′-UTR and suppresses glioma cell malignancy via regulating the expression of cyclin D1, VEGFA, SNAI2, MMP-9, Bcl-2, Bcl-xL and Caspase 3 genes." (PMID 30583549, 2018). "Cheng and colleagues reported apoptosis and decreased levels of Myc, Bcl-2, and Bcl-xL following JQ1 treatment in primary patient-derived glioma xenografts in nude mice." (PMID 29777137, 2018). "In this study, we demonstrated that Bcl-2 was downregulated while the level of Bax, cleaved caspase-3, and TNF-α was increased significantly by RBM5 in gliomas cells, which suggest that RBM5, at least partly, promoted cell apoptosis in gliomas cells." (PMID 28061901, 2017). "Treatment of tumors with CNTFRα siRNA decreased the expression of p-AKT, BCL2 and Ki67, and increased the expression of cleaved Caspase 3 and BAX as observed in CNTRFα siRNA-transfected glioma in vitro." (PMID 28765641, 2017). "Mechanistically, overexpression of KIAA0247 is able to inhibit phosphorylation of AKT and Stat3 in glioma cells, resulting in inactivation of the AKT and Stat3 signaling pathways, this ultimately decreases the expression of PCNA, CyclinD1, Bcl2 and VEGF." (PMID 27893430, 2016). "Expression of Ki67, MMP-9, Cyclin D1, Bcl-2 and C-myc was varied in accordance with the level of TAZ in glioma cell." (PMID 27764783, 2016). "Further analysis using STRING identified four main gene networks (IL-6, BCL2, PTGS2 and CXCR4) that were downregulated in glioma cells silenced for RTVP-1." (PMID 26267319, 2015). "Much research supports a remarkable activity for DMAMCL to glioma, including biodistribution of DMAMCL, potential to inhibit the growth of glioma cells, and probable mechanisms of targeting Bcl-2 signal pathway." (PMID 25658946, 2015). "In glioma cells, ROS induce autophagy by inhibiting mTOR in a BNIP3-dependent manner (BNIP3: BCL2/adenovirus E1B 19 kDa protein-interacting protein 3)." (PMID 25803050, 2015).
glioma (continued). "miR-136 is proposed to be a tumor suppressor in glioma and is capable of targeting the antiapoptosis genes AEG-1 and BCL-2." (PMID 25654102, 2015). "BCL2 silencing resulted in a reduction in glioma cell growth similar to the reduction observed with PAX8 silencing at 48–96 hours post-transfection (P < 0.01, BCL2 siRNA compared with controls)." (PMID 24602166, 2014). "It has been reported earlier that downregulation of cathepsin B can induce apoptosis by suppressing Bcl2 expression and activating BAX accompanied by alternation in mitochondrial membrane potential in human glioma cells." (PMID 24667798, 2014). "Previous studies have shown that glioma cells treated with TMZ exhibit changes in the expression levels of Bax and Bcl-2, which are involved in the mitochondrial pathway of apoptosis." (PMID 24642531, 2014). "For example, lower amounts than expected regarding mRNA levels are noted for MDH1 in GBM and SIRT1 in gliomas; or the protein concentration was increased in glioma tissues, although the mRNA was only slightly modified (typically CCPG1, BCL2, MDM2 and PTBP1)." (PMID 21655185, 2011). "The combination of hypomethylating agents like azacitidine and BCL2 inhibitors like venetoclax has not been formally studied in the treatment of glial tumors." (PMID 38957232, 2024). "AMD is overexpressed in temozolomide-resistant glioma samples, and AMD knockdown augments the effects mediated by temozolomide on the Akt (protein kinase B), extracellular signal-regulated kinases (ERKs) 1/2, and Bax/Bcl-2 signaling pathways." (PMID 39063232, 2024). "According to KEGG database and previous findings, wound healing assay was applied to assess the key apoptosis-related markers, including Bax and Bcl-2, and invasion-related protein, MMP2, for validation the anti-cancer effect and mechanism of ADRA2C drugs in glioma 33-36." (PMID 39308687, 2024). "Targeting Bcl-2 and/or activating BAX to restore caspase-3 activity may be a potential therapeutic strategy for glioma." (PMID 37185746, 2023). "The WB analysis in this study showed that Bcl-2 expression was significantly decreased in AQP8 knockdown glioma cells, whereas Bcl-2 expression was increased and Bax expression was decreased in AQP8 overexpressing glioma cells." (PMID 37280594, 2023). "In another study, a functionalized polymeric micellar system co-loaded with Anti-BCL-2 siRNA and temozolomide reduced the tumor volume in rats and the expression level of BCL-2 in glioma cells in comparison to functionalized micelles containing individual therapy." (PMID 36986837, 2023). "We hypothesized that the AKR1B1 reduces glioma cell proliferation and activates p38 MAPK phosphorylation, thereby mediating the Bcl-2/BAX/caspase-3 pathway." (PMID 37185746, 2023). "Western blotting results indicated that HYAL2 knockdown induced Bcl-2 downregulation, an anti-apoptotic protein, in glioma cells; more importantly, HYAL2 silencing increased the level of BAX, a pro-apoptotic protein, in glioma cells." (PMID 37568202, 2023). "The first high-throughput method to prove that the inhibitory effect of maslinic acid on the growth of human glioma cells may be achieved by the activation of apoptosis induction through MAPK and caspase/Bcl2/Bax signaling pathways." (PMID 35799612, 2022). "Recent studies in glioma also proved that SAA1 knockdown inhibits the phosphorylation of serine/threonine protein kinase B (AKT), which regulates the production of apoptosis-related proteins, such as Bcl2 and Bax, resulting in GBM cell death." (PMID 35756918, 2022).
glioma (continued). "Moreover,we also tested the effect of PTE on apoptosis-related proteins (including Caspase 3 and 9, PARP-1, Bax, Bcl-2 and Survivin) after treated for 24 h, 48 h, 72 h in T98G and LN18 glioma cells." (PMID 33737656, 2021). "The repair of Bcl-2 effectively saved the proliferation and apoptosis of glioma cells lacking LINC01087." (PMID 34459789, 2021). "Overexpression of IGF-I by increasing the expression of Bcl-2 and decreasing the activity of CPP32 could decrease apoptosis in glioma cells." (PMID 33768092, 2021). "Besides, NE promotes the proliferation of glioma cells by regulating the expression of cyclin D1/CDK4/6 and Bcl‐2/Bcl‐XL, while curcumin can reverse these effects to alleviate tumour progression induced by adverse psychological stress." (PMID 34169637, 2021). "Moreover, we validated the expression of Bcl-2, LINC01087, and miR-384 in the glioma cells transfected with shLINC01087 or co-transfected with shLINC01087 and anti-miR-384 or pcDNA-Bcl-2." (PMID 34459789, 2021). "Study have shown that puromycin can induce apoptosis of glioma cells, but its apoptotic mechanism is not exerted through the Fas/Fas ligand pathway and Bcl-2 has only a small protective effect on puromycin-induced apoptosis of glioma cells." (PMID 34164339, 2021). "Overall, the presented data clearly supports our hypothesis that c-IAP2 and Bcl-2 act as SCAP factors in TMZ-induced senescence, and that inhibition of these factors could be used to enhance TMZ-triggered cell death of glioma cells." (PMID 34298797, 2021). "Functional experiments have shown that overexpression of miR-506 could inhibit the migration and invasion of glioma cells and reduce the protein expression levels of MMP2, cyclin D1 and Bcl-2." (PMID 34425834, 2021). "Pre-clinical testing of a microcontroller-based device emitting light of 405 nm wavelength in combination with exposure to 5-ALA (PDT) and the Bcl-2/Bcl-xL inhibitor ABT-263 (navitoclax) was performed in human established and primary cultured glioblastoma cells as well as glioma stem-like cells." (PMID 34439278, 2021). "In glioma, the transfer of linc-CCAT2 to endothelial cells via glioma-derived exosomes resulted in the promotion of angiogenesis via the upregulation of VEGF, TGFβ, and Bcl-2 as well as a reduction of apoptosis via Bax and caspase-3 in vitro." (PMID 31963599, 2020). "Bcl-2 expression was significantly lower in the shXIST group than in the shNC group in both U87 and U251 cells, suggesting that knockdown of XIST mediated glioma cell apoptosis via the Bcl-2 pathway." (PMID 32489472, 2020). "Knockdown of FADD expression decreased TMZ induced PARP1 cleavage, activation of CASP8 and CASP3, and degradation of BCL2 and BCL-XL in ATRX knockout cells, indicating that suppression of FADD is responsible for ATRX mediated PARP1 stabilization and TMZ resistance in glioma cells." (PMID 32194873, 2020). "The identification of natural compounds that serve as Bcl2 inhibitors, such as ALO, might prove to be promising for the eradication of glioma cells." (PMID 31534865, 2019). "We discovered that pro-survival members of the BCL2 family (e.g., BCL2, BCL2L2, BCL2L1, and MCL1), which are overexpressed in glioma (and other tumor) cells and contribute to their resistance to apoptosis inducers, acted as negative modulators of H-1PV-induced apoptosis." (PMID 31216641, 2019). "Unlike GBM cell lines, Bax and Bcl2 were unaltered in C6-glioma and N2a cells, but Cas-3 levels were increased in C6-glioma, while being unaltered in N2a cells after Cur or SLCP treatment, in comparison to vehicle-treated cells." (PMID 30669284, 2019). "CQ can promote this effect through increasing AVd, enhancing the accumulation of cytotoxic protein and reducing anti-apoptotic protein Bcl-2, suggesting that ARHI may be a potential therapeutic target for glioma." (PMID 31088402, 2019).
glioma (continued). "Treatment of glioma cells with ATB-737 and TRAIL has proved to be effective to induce apoptosis by cleaving Bid into tBid, activating caspase-8, and facilitating the accumulation of tBid on the mitochondrial membrane after ABT-737 neutralized Bcl-2 and Bcl-xL." (PMID 30486451, 2018). "Our in vitro experiments in glioma cells confirmed that changes in the expression of CRNDE and miR-136-5p result in changes in Wnt2 and Bcl-2 expression at the mRNA and protein levels, although our study did not provide direct evidence for the corresponding miRNA/mRNA interactions." (PMID 29152149, 2017). "Moreover, curcumin induces G2/M phase arresting in glioma cell via upregulation of p21 and ING4, and further induces apoptosis through up-regulating BAX and down-regulating the Bcl-2 and NF-κB signaling pathway in glioma cells." (PMID 28671583, 2017). "As a tumor suppressor in glioma, lncRNA TUG1 could activate caspase-3 and caspase-9 dependent pathways and suppress Bcl-2 dependent anti-apoptosis pathway." (PMID 28548946, 2017). "In our study, the lethal autophagy induced by overexpression of CERS1 was also independent of Bax and Bcl-2 in glioma cells." (PMID 29262618, 2017). "Overexpression of TUG1 induces apoptosis in glioma cells by activating apoptotic genes caspase-3 and -9-mediated intrinsic pathways and inhibiting anti-apoptotic gene Bcl2-mediated anti-apoptotic pathways, suggesting a tumor suppressor role for TUG1 in human glioma." (PMID 28187439, 2017). "We observed that the expression of apoptosis-related factors (cleaved caspase 3 and Bad) was lower, while the expression of anti-apoptosis (Bcl2), invasion (MMP2 and MMP9) and chemokine pathway related factors (CXCL10 and CXCR3) was higher in glioma tissues than in normal tissues." (PMID 26506595, 2016). "In addition, AKT and STAT3 has been confirmed to be involved in the regulation of downstream factors including PCNA, Bcl2, CyclinD1 and VEGF, which are related to tumor proliferation, apoptosis and angiogenesis in glioma cells." (PMID 27893430, 2016). "In vitro studies reported that inhibition of Bcl-2/Bcl-xL, along with an antitumor agent that induces TRAIL pathway-mediated cell death give a strong synergistic anti-proliferative effect on pediatric, adult, proneural GBM and glioma stem-like cells." (PMID 27344175, 2016). "In this study, we show that TIC10/ONC201, a promising compound that is currently in planned clinical development, along with Bcl-2/Bcl-xL inhibition by ABT263 yields a strong synergistic antiproliferative effect on pediatric, adult, proneural glioblastoma and glioma stem-like cells." (PMID 26474387, 2015). "Because PAX8 binds to the promoter region of BCL2 and WT1 and enhances transcription, we investigated whether the downregulation of PAX8 would decrease the BCL2 and WT1 expression levels in glioma cells." (PMID 24602166, 2014). "MiR-136 was found to promote glioma cell apoptosis by targeting AEG-1 and Bcl-2." (PMID 24373112, 2014). "Glioma cell apoptosis induced by BNCT may be related to activation of Bax and downregulation of Bcl-2." (PMID 21122152, 2010). "We have identified the proportion of cells staining for bcl-2 as a statistically significant prognostic factor in high grade glioma, independent of histological grade." (PMID 12085183, 2002).